MT3 (metallothionein 3)
Diseases named in the same sentence as MT3 in open-access papers (continued):
Sharing a sentence is not in itself a finding about the gene and the disease.
hepatocellular carcinoma (3 papers, 2016 to 2024). A malignant tumor that arises from hepatocytes. "Multifactorial Cox regression of 11 prognostic genes resulted in seven independent risk genes affecting the prognosis of patients with hepatocellular carcinoma, namely ENO1, NDRG1, NPM1, H2AX, IL33, MT3 and TXNRD1." (PMID 38097352, 2023).
lymph node metastasis (3 papers, 2011 to 2022). "Further, down‐regulation of MT3‐MMP significantly correlated with frequency of either lymph node metastasis (P = 0.039) or resected lymph node metastasis (P = 0.017)." (PMID 27292876, 2016).
neuroblastoma (3 papers, 2018 to 2024). Neuroblastoma (NB) is the most common solid, extracranial childhood tumor. "We investigated the impact of human metallothionein-3 (hMT3) up-regulation in neuroblastoma cells and the mechanisms underlying the cisplatin-resistance." (PMID 33750814, 2021). "Metallothionein-3 has poorly characterized functions in neuroblastoma." (PMID 33750814, 2021).
osteoporosis (3 papers, 2021 to 2024). A condition of reduced bone mass, with decreased cortical thickness and a decrease in the number and size of the trabeculae of cancellous bone (but normal chemical composition), resulting in increased fracture incidence. "Downregulation of MT3 by gene knockdown or knockout resulted in excessive osteoclastogenesis and exacerbated bone loss in ovariectomy-induced osteoporosis." (PMID 39085359, 2024). "The function of MT3 in osteoclast differentiation, bone resorption, and osteoporosis was investigated using Mt3 knockout mice." (PMID 39085359, 2024). "Furthermore, in vivo studies of MT3 in the regulation of osteoblast differentiation will be needed to further validate the potential of MT3 to protect against bone-related disorders such as osteoporosis." (PMID 33919218, 2021). "In addition to the impact of Mt3 deficiency on osteoclast differentiation and function in vitro, the present study demonstrated the in vivo significance of MT3-mediated regulation of osteoclasts by employing an OVX-induced osteoporosis model." (PMID 39085359, 2024).
psychosis (3 papers, 2008 to 2023). "In the current cross-study analysis, we identified a set of metallothionein genes including MT1X, MT1K, MT1E, MT1H, MT1F, MT2A and MT3 that are significantly up-regulated in psychosis." (PMID 18992145, 2008). "Using a quantitative PCR, we validated a set of genes such as up-regulated metallothioneins (MT1E, MT1F, MT1H, MT1K, MT1X, MT2A and MT3) and down-regulated neuropeptides (SST, TAC1 and NPY) in the dorsolateral prefrontal cortex of psychosis patients." (PMID 18992145, 2008). "In a study conducted on postmortem subjects with and without psychosis, up-regulation in MT1E, MT1F, MT1H, MT1K, MT1X, MT2A, and MT3 genes was observed in the dorsolateral prefrontal cortex." (PMID 36831126, 2023).
triple-negative breast carcinoma (3 papers, 2015 to 2023). An invasive breast carcinoma which is negative for expression of estrogen receptor (ER), progesterone receptor (PR), and human epidermal growth factor receptor 2 (HER2). "It was found that, in triple-negative breast cancer (TNBC), nuclear MT3 immunoreactivity in cancer cells tended to be associated with patients’ shorter disease-specific survival, suggesting that nuclear MT3 expression may be a potential marker of poor prognosis of triple-negative TNBC cases." (PMID 25933064, 2015). "The MT3 gene, one of the genes affected by cobalt boride exposure, was claimed to have proliferative, cell cycle, and apoptotic effects on cancer cells by regulating the expression of MMP3 in the triple-negative breast cancer (TNBC) cell line." (PMID 36500178, 2022). "In addition, our data point to the negative prognostic impact of nuclear MT3 expression in cancer cells of triple-negative breast cancer." (PMID 25933064, 2015).
Anxiety (2 papers, 2022 to 2025). Intense feelings of nervousness, tension, or panic often arise in response to interpersonal stresses. "Furthermore, MT3 deficiency intensified CFA-induced anxiety- and depression-like behaviors." (PMID 39904985, 2025).
COVID-19 (2 papers, 2022 to 2023). A disease caused by infection with severe acute respiratory syndrome coronavirus 2. "If the expression of metallothionein-3 is upregulated to compensate for intracellular zinc deficiency induced by COVID-19, its inhibitory effect on neurite formation may influence gustatory and saliva secretory functions." (PMID 35330104, 2022). "If metallothionein-3 is age-dependently expressed in taste buds and salivary glands similarly to the brain, such an expression pattern may be associated with the age-dependent characteristics of oral symptoms in COVID-19 patients." (PMID 35330104, 2022). "COVID-19 astrocytes also showed lower levels of Aquaporin-4 (AQP4), and Metallothionein-3 in subsets of COVID-19 brain regions." (PMID 37483351, 2023). "Finally, ventral and lateral ION astrocytes in COVID-19 showed lower levels of AQP4 and MT3, respectively." (PMID 37483351, 2023).
ependymoma (2 papers, 2010 to 2013). A WHO grade II, slow growing tumor of children and young adults, usually located intraventricularly. "Due to poor penetration of zinc into the brain, modulating MT3 expression in ependymomas with this cation would need proper formulations." (PMID 20885975, 2010). "Former descriptions of MT3 inhibition by promoter methylation prompted us to perform a methylation assay on the MT3 gene in ependymomas." (PMID 20885975, 2010). "Metallothionein 3 immunohistochemical expression in ependymomas at diagnosis and relapse." (PMID 20885975, 2010). "To confirm the changes in expression of MT3 and ASPM in an independent cohort, we studied the expression of these two genes on a TMA of childhood ependymomas composed of 24 tumours at diagnosis with at least one relapse." (PMID 20885975, 2010). "Promoter sequencing after bisulfite treatment of DNA from primary tumors and recurrences as well as treatment of short-term ependymoma cells cultures with a demethylating agent showed that methylation was not involved in MT3 downregulation." (PMID 20885975, 2010). "The 5-Aza treatment alone did not increase MT3 expression in the ependymoma cells, while a 2 log increase in expression was found for DAOY." (PMID 20885975, 2010).
epidermoid carcinoma (2 papers, 2014 to 2015). "MT-3 expression was studied using immunohistochemistry in 17 cases of normal skin, 18 of actinic keratosis (AK), 39 of squamous cell carcinoma (SCC), and 23 of basal cell carcinoma (BCC)." (PMID 25015776, 2015).
esophageal adenocarcinoma (2 papers, 2011 to 2018). A malignant tumor with glandular differentiation arising predominantly from Barrett mucosa in the lower third of the esophagus. "Because of MT3s antioxidant functions, we investigated the expression of MT3 and its epigenetic regulation in esophageal adenocarcinoma." (PMID 21818286, 2011). "In this study, we investigated the epigenetic alterations and gene expression of the MT3 gene in esophageal adenocarcinomas (EACs)." (PMID 21818286, 2011). "In conclusion, we demonstrated frequent silencing of MT3 expression in esophageal adenocarcinomas due to unique DNA methylation changes and histone modifications." (PMID 21818286, 2011). "DNA methylation of MT3 was detected in esophageal adenocarcinoma, resulting in MT3 gene silencing." (PMID 30139373, 2018). "We carried out ChIP assay followed by qPCR using two esophageal adenocarcinoma cell lines; FLO-1, which expresses MT3 and has a low level of DNA methylation; and OE33, which has hypermethylated promoter and silenced MT3." (PMID 21818286, 2011).
esophageal cancer (2 papers, 2015). A primary or metastatic malignant neoplasm involving the esophagus. "Recent studies have shown that MT3 is overexpressed in breast, urothelial, prostate, and non-small cell lung cancers; however, downregulation of MT3 has been observed in gastric and esophageal cancers." (PMID 25933064, 2015). "It is possible that MT-3 expression in BCC and basal cells may be the result of similar regulation processes based on DNA methylation, as has been observed in gastric and esophageal cancers." (PMID 25015776, 2015).
Huntington disease (2 papers, 2023 to 2025). Huntington disease (HD) is a rare neurodegenerative disorder of the central nervous system characterized by unwanted choreatic movements, behavioral and psychiatric disturbances and dementia. "Mt3 is a brain zinc binding protein involved in several metabolic processes and has been implicated in cellular dysfunction of diseases including Alzheimer and Huntington disease." (PMID 40000848, 2025).
macular degeneration (2 papers, 2019 to 2024). Loss of vision in the central portion of the retina (macula), secondary to retinal degeneration. "This suggests that acupuncture may target specific genes involved in the treatment of glaucoma, such as MT3 (associated with ocular neovascularization) and FBN1 (related to macular degeneration)." (PMID 39378079, 2024).
metastatic tumors (2 papers, 2011 to 2018). "Unlike the strongly pro-invasive MT1-MMP that is widely overexpressed in the aggressive and metastatic tumors, MT3-MMP expression has been reported in only a few tumor types." (PMID 22164270, 2011).
myopia (2 papers, 2017 to 2019). "MT3 can inhibit form deprivation myopia, and MT3 treatment can result in changes of retinal and choroidal TGF-β2 and HAS2 mRNA and protein expressions." (PMID 29163988, 2017). "This indicates that MT3 is also effective in inhibiting myopia development of guinea pigs in a dose-dependent manner." (PMID 29163988, 2017). "Since TGF-β2 and HAS2 may be involved in the development of form deprivation myopia, in a second step, we studied the effect of MT3 at different tissue concentrations on changes in mRNA and protein expression for TGF-β2 and HAS2." (PMID 29163988, 2017). "Off‐target binding of drugs is not a well‐studied line of inquiry, but there is interesting evidence from the chick form‐deprivation model that supports a role for off‐target, and not muscarinic, receptor effects for myopia treatment with high concentrations of atropine, himbacine, and MT3." (PMID 30699466, 2019).
non-small cell lung carcinoma (2 papers, 2015). A group of at least three distinct histological types of lung cancer, including non-small cell squamous cell carcinoma, adenocarcinoma, and large cell carcinoma. "In our recent study, nuclear MT3 expression was also observed in pneumocytes and cancer cells of non-small cell lung cancers." (PMID 25933064, 2015). "Augmented MT-3 expression was observed in neoplastic cells of breast, prostate, bladder, and non-small-cell lung cancer." (PMID 25015776, 2015). "In addition to normal tissues, high expression of MT3 has been reported in several types of cancers, including urinary bladder, breast, prostate and non-small cell lung cancers." (PMID 25933064, 2015).
oral cancer (2 papers, 2016 to 2023). "Through weighted gene coexpression network analysis (WGCNA), we found that MT3 is associated with cisplatin resistance in oral cancer, and our results suggest a different mechanism of chemotherapy resistance in oral cancer than previously known." (PMID 38041044, 2023). "The expression of MT3 in oral cancer cells promotes the expression of YAP1, thereby regulating the stemness of tumor cells." (PMID 38041044, 2023). "According to the WGCNA results, MT3 is most closely related to drug resistance in patients with oral cancer, and patients with high expression of MT3 have a worse prognosis." (PMID 38041044, 2023). "We found that MT3 expression was higher in chemotherapy-resistant oral cancer patients than in chemotherapy-sensitive patients." (PMID 38041044, 2023). "We found that MT3 may mediate the chemotherapy resistance of oral cancer through YAP1." (PMID 38041044, 2023). "However, there has been no report on MT3 and chemoresistance in oral cancer." (PMID 38041044, 2023).
pancreatic cancer (2 papers, 2021). "Studies have shown that MMP-1, MMP-2, MMP-7, MMP-9, membrane type 1-MMP (MT1-MMP), MT2-MMP, and MT3-MMP are overexpressed in pancreatic cancer tumors, while MMP-2, MMP-7, and MMP-9 have been identified as potential biomarkers of pancreatic cancer." (PMID 34809634, 2021).
selenium deficiency (2 papers, 2021 to 2025). A nutritional deficiency disease resulting from inadequate selenium levels in the body, which can lead to impaired function of selenoproteins essential for antioxidant defense and thyroid hormone metabolism. "The researchers also found that selenium deficiency could induce the release of Zn2+ from stores, although the Zn2+ storage protein metallothionein-3 (MT3) was elevated, and Zn2+ transporters, ZnT1 and ZnT2, were unchanged." (PMID 39941073, 2025). "Although the Zn2+ storage protein MT3 was elevated without change to the zinc transporters ZnT1 or ZnT3, we showed that selenium deficiency could induce release of Zn2+ from stores, likely through a decrease of the selenoprotein GPX4 and a subsequent increase in lipid peroxidation." (PMID 34277682, 2021).
Stroke (2 papers, 2015 to 2020). Sudden impairment of blood flow to a part of the brain due to occlusion or rupture of an artery to the brain. "Especially, the function of MT3 in oxido-reduction reaction is important in suppressing the early stages of various diseases such as stroke, cardiomyopathy, diabetic retinopathy, and cancer." (PMID 32843100, 2020).
Zinc deficiency (2 papers, 2016 to 2022). A deficiency of the essential metal Zinc; an essential cofactor for many enzymes. "The influence of intracellular zinc deficiency should be more significant on the tissues where metallothionein-3 is increasingly expressed and localized." (PMID 35330104, 2022). "A moderate increase of MT3 expression in response to zinc deficiency was reported before in rats." (PMID 27247802, 2016).
adenomyosis (1 paper, 2022). The growth of endometrial tissue inside the muscular wall of the uterine corpus. "In contrast, MT2-MMP and MT3-MMP protein was decreased in ectopic compared to eutopic endometrium and adenomyosis." (PMID 35453827, 2022). "Interestingly, we identified a reduced MT2-MMP and MT3-MMP protein expression in endometriosis but not in adenomyosis." (PMID 35453827, 2022). "We analyzed MT2-MMP (MMP15) and MT3-MMP (MMP16) in eutopic endometrium with and without endometriosis and with and without adenomyosis and ectopic endometrium of deep infiltrating endometriosis (DIE), peritoneal endometriosis (PE), and ovarian endometriosis (Ov) by immunohistochemistry." (PMID 35453827, 2022).
alpha-synucleinopathy (1 paper, 2017). "MT-1/2 expression is increased in activated astrocytes in alpha-synucleinopathies, yet expression of the neuronal MT-3 isoform may be reduced." (PMID 28420950, 2017).
Arthritis (1 paper, 2025). Inflammation of a joint. "MT3-deficient mice exhibited a pronounced reduction in body mass and significantly elevated arthritis scores compared to those in the control groups." (PMID 39904985, 2025). "Notably, treatment with 1 or 10 mg/kg ZnCl2 in the MT3 KO + CFA group significantly restored arthritis scores, reflecting Zn2+ concentration-dependent recovery." (PMID 39904985, 2025). "Additionally, the MT3 + CFA group, treated with either 1 or 10 mg/kg TPEN, demonstrated a notable increase in arthritis scores compared to scores in the MT3 WT + CFA group in a TPEN concentration-dependent manner." (PMID 39904985, 2025). "The MT3 WT + CFA group displayed an increase in arthritis scores compared with those in the non-CFA control group, whereas the MT3 KO + CFA group showed a substantial increase in arthritis scores relative to those in the MT3 WT + CFA group." (PMID 39904985, 2025).
bladder tumor (1 paper, 2019). "It is possible that overexpression of MT3 is one of the mechanisms of bladder tumor cell resistance to cancer treatment." (PMID 30813460, 2019).
brain tumor (1 paper, 2010). "In this work, we show the possibility to induce MT3 expression with zinc in brain tumor (EP and medulloblastoma) cells." (PMID 20885975, 2010).
colonic tumor (1 paper, 2007). "Since the oxidative/nitrosative stress caused by DSS in the colonic mucosa contributes to colonic tumor development in our inflammation-related mouse colon carcinogenesis model, Mt-3 might be up-regulated to protect cells from oxidative stress." (PMID 17506908, 2007).
depression (1 paper, 2025). "We demonstrated the role of MT3 in an MT3 knockout mouse model of inflammatory pain in the paw, highlighting the necessity of intracellular Zn2+ and its interplay with MT3 in mitigating pain- and depression-related behaviors." (PMID 39904985, 2025).
diabetic nephropathy (1 paper, 2025). "In the pathological process of diabetic nephropathy, hypoxia can activate hypoxia-inducible factor-alpha (HIF-α) in renal tubular epithelial cells, which in turn induces high expression of Metallothionein 3 (MT3)." (PMID 41480358, 2025).
E. coli infection (1 paper, 2021). "We demonstrate that while MT3 orchestrates negative regulation of the caspase-11 inflammasome, the combined presence of MT3 and caspase-11 blunts resistance to E. coli infection in vivo." (PMID 34867993, 2021).
endometriosis (1 paper, 2022). The growth of functional endometrial tissue in anatomic sites outside the uterine body. "In contrast, the percentage of MT3-MMP-positive glands was significantly reduced only in deep infiltrating endometriosis compared to eutopic endometrium (p ≤ 0.05)." (PMID 35453827, 2022). "Preferential expression of both proteins was observed in the glandular and luminal epithelial cells of the eutopic endometrium of patients with and without endometriosis with a ~2.5-fold stronger expression of MT3-MMP compared to MT2-MMP." (PMID 35453827, 2022). "Endometrial glandular epithelial cells showed strong staining of MT3-MMP in a very high percentage of glands across the menstrual cycle in eutopic endometrium of patients with and without endometriosis." (PMID 35453827, 2022). "In the present study, we investigated MT2-MMP and MT3-MMP expression pattern in eutopic and ectopic endometrial tissues collected from patients with and without endometriosis." (PMID 35453827, 2022). "Similarly, eutopic endometrium and adenomyotic tissue with and without endometriosis showed similar protein levels of MT2-MMP and MT3-MMP." (PMID 35453827, 2022).
esophageal tumors (1 paper, 2025). "Initial research indicates that MT3 is predominantly found in the central nervous system; however, it is present in several peripheral organs and various human cancers, such as prostate, lung, breast, urothelial, and esophageal tumors, among others." (PMID 40860678, 2025).
gram-negative bacterial infections (1 paper, 2021). Infections caused by bacteria that show up as pink (negative) when treated by the gram-staining method. "Our data unveil a unique crosstalk between caspase-11 and its negative regulator, whereby although MT3 keeps caspase-11 activation under control, the two synergistically compromise host immunological fitness to gram-negative bacterial infection." (PMID 34867993, 2021).
gram-positive bacterial infections (1 paper, 2021). Infections caused by bacteria that retain the crystal violet stain (positive) when treated by the gram-staining method. "We determined whether the increased non-canonical inflammasome activation and antibacterial resistance observed in Mt3-/- mice extended to gram-positive bacterial infection." (PMID 34867993, 2021).
Hyperglycemia (1 paper, 2017). An increased concentration of glucose in the blood. "In this regard, more recent studies on the zinc-rich insulin producing islet β-cells suggest a role for MT-3 in streptozotocin (STZ)-induced islet cell death and consequent hyperglycemia." (PMID 28538697, 2017).
in situ breast cancer (1 paper, 2017). "A high frequency of MT3 staining was also demonstrated for in situ breast cancer, suggesting MT3 might be an early biomarker for disease development." (PMID 28545470, 2017).